INS (insulin)
Diseases named in the same sentence as INS in open-access papers (continued):
Sharing a sentence is not in itself a finding about the gene and the disease.
Insulin resistance (continued). "Fasting glucose was approximately 14% higher in males (p < 0.001), while insulin and HOMA-IR levels were elevated by over 140% and 170%, respectively (p < 0.001 for both), consistent with greater insulin resistance." (PMID 40754228, 2025). "Insulin can inhibit VLDL production, and VLDL production increases and the clearance decreases in insulin resistance (IR)." (PMID 40723862, 2025). "Elevated circulating amino acid levels, particularly of BCAAs such as Leu, Ile, and Val, can interfere with insulin signaling by reducing tyrosine phosphorylation of insulin receptor substrates (IRS-1 and IRS-2), thereby contributing to insulin resistance." (PMID 40806262, 2025). "△HSDS for SA negatively correlated with baseline homeostasis model assessment of insulin resistance (HOMA-IR) and fasting insulin, and positively correlated with baseline free triiodothyronine (FT3)." (PMID 41282298, 2025). "In summary, we found that administering CJE to db/db mice at 200 mg/kg improved fasting blood glucose, serum insulin, serum leptin, and HOMA-IR levels, indicating a potential improvement in insulin resistance." (PMID 39815341, 2025). "This inflammatory state disrupts insulin signaling, with cytokines such as tumor necrosis factor‐alpha (TNF‐α) and interleukin 6 (IL‐6) leading to insulin resistance and complications such as type 2 diabetes." (PMID 40968498, 2025). "Research suggested that administering HFD for a specific duration triggered insulin resistance, while a low dose of STZ induces mild impairment in insulin secretion." (PMID 40448078, 2025). "TNF attenuates the insulin-stimulated tyrosine phosphorylation of IRS1 in adipose tissue and muscle, resulting in the occurrence of insulin resistance." (PMID 39812542, 2025). "Because PI3K–AKT is the principal insulin pathway in the liver and muscle, EV-mediated AKT inhibition provides a direct paraneoplastic route to insulin resistance." (PMID 41226286, 2025). "The homeostasis model assessment of insulin resistance (HOMA-IR) is the most widely used surrogate marker of insulin resistance, but it has limited applicability in individuals receiving insulin treatment." (PMID 40363995, 2025). "A meta-analysis of 12 randomised trials showed that in 10 of these, Lactobacillus strains significantly reduced HbA1c, fasting insulin, and the HOMA-IR insulin resistance index in individuals with T2D." (PMID 41154691, 2025). "Insulin resistance or low insulin sensitivity is indicated by a high HOMA-IR value, while high insulin sensitivity is indicated by a low HOMA-IR reading." (PMID 40365311, 2025). "Among the tools used to assess IR risk, notable indices included the Triglyceride-Glucose Index (TyG), the Metabolic Score for Insulin Resistance (METS-IR) and the Single-Point Insulin Sensitivity Estimator (SPISE)." (PMID 40281870, 2025). "N = number; IR = Insulin Resistance; SD = standard deviation; SBP = systolic blood pressure; DBP = diastolic blood pressure; HOMA-IR = homeostatic model assessment for insulin resistance; QUICKI = quantitative insulin sensitivity check index." (PMID 41271970, 2025). "In a cross-sectional study evaluating the effect of SGLT2 inhibitors on insulin secretion and resistance, SGLT2 inhibitors blunted glucagon-induced insulin secretion in β-cells and improved insulin resistance." (PMID 40149704, 2025). "Skeletal muscle (glucose infusion rate/steady‐state insulin) insulin sensitivity and hepatic (HOMA‐IR) as well as adipose (Adipose‐IR) insulin resistance were assessed during a 120 min euglycemic hyperinsulinemic clamp (40mU/m2/min, 90 mg/dL)." (PMID 40018087, 2025). "Metaanalyses have reported beneficial changes in insulin sensitivity, fasting glucose, triglycerides, and LDL cholesterol, particularly in individuals with insulin resistance or metabolic syndrome." (PMID 41515130, 2025).
Insulin resistance (continued). "ANT2 knockdown improves insulin sensitivity and reduces adipocyte hypoxia and Genetic deletion of ANT2 protects diet-induced liver steatosis and insulin resistance." (PMID 40869061, 2025). "In diabetic patients and indeed all patients with insulin resistance, the presence of both hyperglycemia and genetically determined GLP-1 resistance can potentiate the impairment of GLP1-induced insulin secretion." (PMID 40424240, 2025). "Our data revealed that, in the HBER ampulla, the miRNA-containing EVs are involved in insulin resistance, similar to what has been observed in AMP-Cell, and we suggest that the insulin pathway is disrupted within the ampulla of HBER animals." (PMID 40549708, 2025). "These benefits include decreases in fasting insulin levels, insulin resistance, IGT, triacylglycerol levels and fasting glucose levels and improvements in insulin sensitivity." (PMID 39861423, 2025). "Compared with the ND group, HFD group mice exhibited significantly elevated fasting blood glucose (FBG), fasting serum insulin (FSI), and homeostasis model assessment of insulin resistance (HOMA-IR)." (PMID 41024248, 2025). "Recent research has been shown that activation of the NLRP3 inflammasome in adipocytes reduces insulin-dependent glucose uptake and contributes to TNF-α-induced insulin resistance." (PMID 40583106, 2025). "In our own validation, we performed an insulin tolerance test, showing that STZ-HFD animals exhibited poor glucose clearance in response to exogenous insulin, a key feature of insulin resistance." (PMID 41047888, 2025). "This suggests that assessing insulin resistance at baseline could help stratify patients likely to benefit from adjunctive therapies targeting insulin sensitivity to enhance rhGH responsiveness, as hyperinsulinemia is increasingly recognized as a key disruptor of the insulin-GH balance." (PMID 41282298, 2025). "In the same groups, plasma insulin concentration and fasting blood glucose (FBG) levels were measured to calculate the Homeostatic Model Assessment of insulin resistance (HOMA-IR)." (PMID 40564980, 2025). "For instance, a study on insulin-resistant mice found that long-term FGF21 treatment activated the FAO signaling pathway, leading to improved cardiac metabolism, reduced insulin resistance, enhanced FGF21 sensitivity, and better overall cardiac function." (PMID 40036545, 2025). "It helps enhance insulin sensitivity, which is a critical concern for many women with PCOS who experience insulin resistance." (PMID 41041518, 2025). "Outcomes assessed included systolic BP (SBP), diastolic BP (DBP), heart rate (HR), fasting blood glucose (FBG), fasting insulin (FINS), homeostasis model assessment of insulin resistance (HOMA-IR), and body mass index (BMI)." (PMID 41346676, 2025). "At a dose of 60 mg/kg, it lowered the plasma glucose, insulin, triglyceride, and LDL levels, suggesting its potential for mitigating insulin resistance." (PMID 40729034, 2025). "Ceramides induce cellular stress and death, impairing muscle insulin sensitivity by decreasing AKT, and PKB activity, and serve as primary inflammatory mediators of muscle insulin resistance." (PMID 40881124, 2025). "To further investigate the relationship between the high-IRRS group and insulin resistance, we performed GSEA on the insulin-related pathway." (PMID 40427728, 2025). "Although fasting insulin was included as a predictor, the HOMA-IR index would provide a more accurate reflection of insulin resistance." (PMID 40431396, 2025). "This study revealed that the TyG index had a good correlation with indices reflecting insulin resistance, such as BMI, WC, HOMA-IR score, WBC count, and fasting insulin, as well as FPG, HbA1c, HDL-C, TG, ferritin, and CRP levels." (PMID 40507147, 2025). "In sucrose-fed (SF) rats with insulin resistance, phosphorylation of Akt (PKB)—a central molecule in the insulin signaling pathway—was reduced compared to normal animals." (PMID 40806520, 2025).
Insulin resistance (continued). "Five weeks after AAV8 transduction, we assessed glucose clearance and insulin resistance using glucose tolerance tests (GTT) and insulin tolerance tests (ITT), respectively." (PMID 40278833, 2025). "In adipocytes, MIF-driven TNF-α secretion contributes to insulin resistance, while in endothelial cells, MIF disrupts insulin-mediated nitric oxide release, fostering endothelial insulin resistance." (PMID 41036138, 2025). "A retrospective cohort study in 65 surgery candidates with PHPT showed lower fasting plasma glucose, insulin, HbA1c, HOMA-IR, and a reduction the insulin resistance prevalence (32.3% vs. 23.1%, p = 0.031)." (PMID 40283231, 2025). "The phosphatase and tensin homolog (PTEN) protein is a negative regulator of insulin signaling, and Cu reduces PTEN levels in mouse adipocytes, enhancing insulin resistance." (PMID 41268170, 2025). "In agreement, F rats exhibited systemic insulin resistance, while we here show for the first time that the administration of S. clausii SF174 spores was effective in preserving insulin sensitivity." (PMID 40207597, 2025). "Secondary outcomes revealed meaningful improvements in several metabolic parameters, including fasting blood glucose and insulin resistance (HOMA‐IR), supporting pioglitazone's insulin‐sensitising effects." (PMID 40420634, 2025). "Insulin levels decreased significantly (p = 0.018), along with a marked reduction in HOMA-IR (p = 0.007), reflecting improved insulin resistance." (PMID 40428900, 2025). "As insulin resistance progresses, VAT becomes less responsive to insulin's antilipolytic effects, further increasing the release of FFA and glycerol, ultimately perpetuating hepatic lipid overload and progressive insulin resistance." (PMID 41190377, 2025). "These glycemic improvements were accompanied by lower insulin resistance, as measured by the HOMA-IR (p = 0.05), and greater insulin sensitivity, as measured by the QUICKI (p < 0.02)." (PMID 40941087, 2025). "Herein, our study demonstrated that insulin resistance occurs in both adipose tissue and skeletal muscle of ASKO mice, while hepatic insulin sensitivity under insulin stimulation remains unaffected." (PMID 40522008, 2025). "It is known that rats fed a low‐protein diet exhibit reduced serum insulin and insulin‐like growth factor I (IGF‐I) levels, along with increased insulin resistance." (PMID 41282546, 2025). "In-depth exploration of the relationship between Metrnl and insulin resistance, as well as the occurrence and development of T2DM, is crucial for understanding the molecular mechanisms that regulate insulin synthesis and energy metabolism homeostasis." (PMID 40956671, 2025). "A much simpler method to assess insulin resistance for large-scale application is the homeostasis model assessment of insulin resistance (HOMA-IR) using glucose and insulin dosages in fasting conditions with a good correlation coefficient with HEC values." (PMID 40217851, 2025). "Exosomal Mst1 from endothelial cells promotes apoptosis by inhibiting autophagy and insulin signalling, thereby impairing GLUT4 membrane translocation and insulin resistance." (PMID 40243689, 2025). "Key findings include the disruption of insulin signaling pathways due to aberrant phosphorylation of IRS-1 and IRS-2, resulting in impaired glucose uptake and insulin resistance." (PMID 39519193, 2024). "Homeostasis model assessment-adiponectin (HOMA-AD), homeostasis model assessment of insulin resistance (HOMA-IR), quantitative insulin sensitivity check index (QUICKI), triglyceride-glucose index (TyG), and atherogenic index of plasma (AIP) were calculated." (PMID 38927429, 2024). "β-cell function included insulin resistance (HOMA-IR), insulin sensitivity (Matsuda index (MI)), and insulin secretion evaluated by HOMA-β and C-peptidogenic index (CGI)." (PMID 39376578, 2024).
Insulin resistance (continued). "A validated alternative evaluation index is the homeostatic model assessment of insulin resistance (HOMA-IR), which is calculated from fasting blood glucose and insulin concentrations." (PMID 38419039, 2024). "Regarding insulin sensitivity, we confirmed that HFD feeding induces peripheral insulin resistance in rats, as judged by the intraperitoneal insulin tolerance test." (PMID 38399437, 2024). "Insulin sensitivity indices include the Matsuda index, the Quantitative Insulin Sensitivity Check Index (QUICKI), and the Homeostatic Model Assessment for Insulin Resistance (HOMA-IR)." (PMID 39726936, 2024). "Among these alternatives, the most widely used indicator for IR is the homeostatic model assessment of insulin resistance (HOMA-IR), an index calculated using fasting insulin (FINS) and fasting plasma glucose (FPG)." (PMID 39021592, 2024). "Hyperglycemia and altered insulin signaling in T1DM, along with hyperglycemia, insulin resistance, and dyslipidemia in T2DM, result in dysfunction of the endoplasmic reticulum and mitochondria, systemic inflammation, and oxidative stress (OS)." (PMID 39598447, 2024). "Patients in Group 3 and Group 4 displayed elevated levels of fasting glucose, fasting insulin, and fasting C-peptide, along with increased values of the HOMA-IR, indicating heightened insulin resistance." (PMID 39439559, 2024). "The model assessed insulin resistance (HOMA-IR) and islet β-cell function (HOMA-β) only by using FBG and fasting insulin values." (PMID 38969755, 2024). "Both acute or chronic aerobic and resistance exercise enhances insulin sensitivity, suggesting that exercise likely reduces DAG levels by repairing the MAMs structure, thereby alleviating insulin resistance (IR)." (PMID 38542170, 2024). "In terms of metabolic parameters, VLCKD treatment effectively reduced fasting blood glucose, insulin, triglycerides, total cholesterol, LDL cholesterol, HDL cholesterol, γGT, and insulin resistance." (PMID 38542785, 2024). "Homeostatic model assessment of insulin resistance index (HOMA-IR) was increased and glucose effectiveness derived from the IVGTT and Matsuda ́s insulin sensitivity index from the MMT were decreased in the HFD groups." (PMID 38427692, 2024). "Moreover, emerging research suggests that patients with psychotic disorders may display varying degrees of insulin resistance in the early stages of the disorder, exhibiting greater fluctuations in glucose, insulin, and lipid parameters compared to the healthy control group." (PMID 38463431, 2024). "A bidirectional relationship has been suggested between insulin levels and lipid metabolism, including HDL-C levels, which are often found to be reduced in individuals with insulin resistance." (PMID 39408385, 2024). "The supported mechanism includes insulin resistance characterizing early AAM, which is further aggravated by the metabolic stress of pregnancy and the excess insulin demand." (PMID 38498127, 2024). "This dysfunction of the insulin/IGF signalling pathway in metabolic organs and tissues can lead to insulin resistance, cellular death, and metabolic abnormalities." (PMID 38651404, 2024). "We measure fasting insulin and glucose at baseline, 4 months, and 12 months using standard assays from LabCorp to determine HOMA-IR, a widely used method of estimating insulin resistance from a single fasting blood draw." (PMID 39516828, 2024). "At baseline, there were significant differences between men and women in terms of anthropometric parameters, blood pressure, Homeostatic Model Assessment for Insulin Resistance (HOMA-IR), fasting insulin, hepatic markers, and lipid profile." (PMID 38794646, 2024). "Targeted knockout or ablation of INSR in the liver results in the inability of insulin to suppress hepatic glucose production (HGP), highlighting the critical role of INSR in hepatic insulin resistance." (PMID 39125938, 2024).
Insulin resistance (continued). "Attention is directed towards insulin resistance (TLS = 39, 49 links), insulin (TLS = 11, 38 links), blood glucose (TLS = 12, 40 links), and identification of molecular biomarkers (TLS = 10, 39 links)." (PMID 39376657, 2024). "Fasting insulin, PAI, homeostasis model assessment of insulin resistance (HOMA-IR), and HOMA-β were significantly higher and quantitative insulin sensitivity check index (QUICKI) was considerably lower in patients with IR compared to those without IR." (PMID 39275320, 2024). "Surrogate markers of insulin resistance such as HOMA-IR, fasting insulin, HDL, and triglycerides have been evaluated in small studies." (PMID 39328462, 2024). "Seven studies evaluated the insulin dose difference between the intervention and control group and HOMA, an indicator of insulin resistance." (PMID 39593185, 2024). "Fasting plasma glucose (FPG), 2-h post-prandial blood glucose (2-h PG), HbA1c, fructosamine, fasting insulin level (FINS), insulin resistance index (HOMA-IR), and insulin sensitivity index (HOMA-IS) were evaluated." (PMID 38575692, 2024). "The inflammatory cascade can downregulate glucose transporters and insulin-related molecules (such as GLUT4, cyclin A, cyclin E, and IRS-1), leading to elevated blood glucose and insulin resistance in patients with T2DM." (PMID 38396669, 2024). "We also added details of the insulin resistance-related biomarker, including HOMA-IR, blood glucose, and insulin level, in the PCoA plot." (PMID 38902371, 2024). "In this study, insulin resistance index (HOMA-IR) and fasting insulin levels were statistically significantly higher in patients than in controls and glucose intolerant patients when compared to normal ones." (PMID 38575692, 2024). "We also investigated the relationship between KITT(iv) and the parameters related to obesity and insulin resistance and examined the possible role of KITT(iv) in predicting the insulin dose required for glycemic control in patients with T2DM." (PMID 38905235, 2024). "FI: fasting insulin, FG: fasting glucagon, IGR: insulin:glucagon ratio, HOMA-IR: homeostatic model assessment for insulin resistance, HbA1c: glycated hemoglobin." (PMID 38665134, 2024). "This also limited our assessment of insulin resistance to HOMA-IR, which is measured using fasting blood glucose and fasting insulin and is commonly used in clinical settings due to its simplicity and non-invasiveness." (PMID 39685880, 2024). "This suggests that RE can effectively decrease insulin resistance in GDM and enhance insulin sensitivity." (PMID 39481539, 2024). "Additionally, one of our previous studies in Nigerians has reported that patients with T2D have an atypical metabolic presentation characterized by both insulin resistance and reduced insulin secretion, but the molecular characteristics that may be involved in these changes are unknown." (PMID 38444015, 2024). "Thus, insulin resistance could be either a contributing factor to or a consequence of obesity, as adipose tissue generates pro-inflammatory cytokines and adipokines that directly influence insulin metabolism." (PMID 39767952, 2024). "The biological effects of insulin are integral to the PI3K/Akt signaling pathway, and lipid metabolism is intricately connected to lipids, atherosclerosis, and insulin resistance." (PMID 39201413, 2024). "Homeostatic Model Assessment of Insulin Resistance (HOMA-IR), Homeostatic Model Assessment of Beta Cell Function (HOMA-B), and Quantitative Insulin Sensitivity Check Index (QUICKI) were calculated using standard formulas." (PMID 38872654, 2024). "Previous studies have suggested that 20-HETE impairs insulin signaling through GPR75 activation and contributes to the development of insulin resistance." (PMID 39137039, 2024). "Insulin resistance (IR) was determined by HOMA-IR, calculated from plasma insulin and glucose values according to HOMA-IR = Fasting insulin (μU/ml) x fasting glucose (mg/dL)/405." (PMID 39372725, 2024).